VTN (vitronectin)
Diseases named in the same sentence as VTN in open-access papers (continued):
Sharing a sentence is not in itself a finding about the gene and the disease.
glioma (23 papers, 2007 to 2026). A benign or malignant brain and spinal cord tumor that arises from glial cells (astrocytes, oligodendrocytes, ependymal cells). "An increase in circulating vitronectin has previously been proposed as a diagnostic and prognostic biomarker for glioma." (PMID 34641541, 2021). "Cilengitide induces apoptosis in U87 glioma cells by inhibiting adherence to vitronectin and tenascin, proteins that mediate brain tumor invasion and growth." (PMID 40598793, 2025). "Accordingly, CD155 expression enhances tumor spreading in primary gliomas, and its over-expression in glioma cell lines reduces adhesion to vitronectin and induces cell migration." (PMID 37629138, 2023). "Integrin αV is part of the so called RGD-binding integrin subgroup, a target motif in ECM components like fibronectin and vitronectin, and is particularly important in glioma pathogenesis." (PMID 35484633, 2022). "Accordingly, Vitronectin, Fibronectin, and Tenascin C expression is correlated with increasing invasiveness and a higher glioma grade." (PMID 35053605, 2022). "In glioma, vitronectin is present not only in the serum but also in the cerebrospinal fluid and induces glioma cell migration in vitro." (PMID 33206391, 2021). "Three peptides of 5 Proteins which includes APOA1, APOE, PTGDS, VTN and C3 were monitored for both Meningioma and Glioma samples." (PMID 34055594, 2021). "Our MRM data from CSF of gliomas also suggests a significant up-regulation of VTN in GBMs as compared to LGGs, one of the interactors of Integrins." (PMID 34055594, 2021). "First, to compare CT and PVZ GSCs migration properties, we performed spreading assays on laminin, fibronectin and vitronectin, three extracellular matrix proteins found in the basement membrane of brain blood vessels and involved in glioma pathogenesis." (PMID 30333910, 2018). "A possible cause of the protective effect of TSP-1 silencing by hypermethylation in GBM and OD is that TSP-1 is pro-migratory at the border of gliomas, as are other proteins secreted by glioma cells such as laminins, vitronectin and fibronectin." (PMID 25621889, 2015). "Treatment of SF1126 for 30 minutes caused a significant change in the organization and distribution of cortical actin on vitronectin in the glioma cells." (PMID 25425962, 2014). "We therefore tested the effect of SF1126 on the vitronectin-mediated migration of glioma cells derived from the transgenic mouse in transwell migration chambers." (PMID 25425962, 2014). "Most notably, treatment of SF1126 blocked integrin-dependent migration in transwell and scratch assays and caused a significant change in the organization and distribution of cortical actin on vitronectin in the glioma cells." (PMID 25425962, 2014). "We interpret that the inhibition of migration of glioma cells on vitronectin following SF1126 treatment is in part due to its inhibitory effect on integrin-mediated activation of PI3-kinase pathway." (PMID 25425962, 2014). "Our results show a significant blockade of vitronectin-mediated migration in the glioma cells from 12 V-Ha-Ras transgenic mice in presence of SF1126." (PMID 25425962, 2014). "VTN is one of the main factors that induces tumor migration in glioma." (PMID 36676646, 2022). "Serum levels of vitronectin correlate with glioma grade and predict outcome." (PMID 33206391, 2021). "Our data are in agreement with other studies on non-glioma cells showing that collagen- or vitronectin-related integrins may be able to stimulate the beta-catenin pathway." (PMID 27613837, 2016). "We argue that the inhibitory effects of SF1126 observed on vitronectin-mediated migration in glioma cells may be mediated through its effects on both RAS-MAP-kinase and PI3-kinase pathways." (PMID 25425962, 2014). "Vitronectin is also known to be induced in glioma cells, which enhanced the cell migration." (PMID 23704872, 2013). "In addition, integrin heterodimers αvβ1 and αvβ3 are receptors for vitronectin and are upregulated on glioma cells." (PMID 22363471, 2012).
glioma (continued). "Like MGP, vitronectin expression in gliomas is known to increase with tumor grade in vivo." (PMID 19712474, 2009). "The collagen and glycoprotein profiles in pediatric HGGs showed partial overlap with adult tumors, with three of the top glycoproteins in adult gliomas (VTN, TNR, and PLG) also among the most highly expressed proteins in pediatric gliomas." (PMID 40517137, 2025). "Here, we detailed the highly altered proteins (COL1A1, FN1, VTN, etc.)and the phosphosite (FN1_T1642) in the extracellular matrix (ECM) of BrM, as compared to primary brain tumor gliomas." (PMID 39716938, 2025). "In glioma cells, CD155 mediates adhesion to the extracellular matrix protein vitronectin, promotes FA turnover and FA signaling towards SRC, paxillin, and p130CAS, and thereby contributes to tissue invasion." (PMID 35296518, 2022). "While cumulative fold change of three peptides of VTN, PTGDS and C3 in GBM were found to be upregulated in GBM as compared to low grade glioma." (PMID 34055594, 2021). "The glycoprotein vitronectin is involved in cell adhesion, growth, and migration and has been shown to protect GBM cells from apoptosis and to promote glioma cell migration." (PMID 34641541, 2021). "The expression levels of proteins such as VTN, APOA1 and PTGDS were found to be highly up regulated in GBM as compared to low grade gliomas." (PMID 34055594, 2021). "Several of the components identified in glioma ECMs are permissive substrates enhancing cell migration, but like the interaction of MGP and vitronectin, effects can be modulated by additional ligands or modifications." (PMID 19712474, 2009). "It is a multifunctional RNA-binding protein that is overexpressed in glioma, a type of tumor that occurs in the brain, and a decreased expression of PTBP inhibits cell migration and increases the adhesion of cells to fibronectin and vitronectin." (PMID 34132195, 2021).
melanoma (23 papers, 2006 to 2025). A malignant, usually aggressive tumor composed of atypical, neoplastic melanocytes. "However, an analysis based on classification together with multivariate statistics showed that tumor stage, vitronectin and dermcidin levels were associated with the metastatic progression of patients with early‐stage melanoma." (PMID 27216146, 2016). "Moreover, the expression of vitronectin (αvβ3) in melanoma cells has been associated with increased invasiveness." (PMID 25231141, 2014). "Tzabcanin (Crotalus simus tzabcan) was able to inhibit the adhesion of melanoma cell line A-375 to vitronectin, exhibiting weak cytotoxicity." (PMID 39594665, 2024). "For example, the vitronectin αvβ3 integrin receptor allows melanoma cells to attach to ECM components via the Arg–Gly–Asp peptide sequence." (PMID 39594665, 2024). "Reduction in melanoma cell adhesion to vitronectin with an IC50 of 747 nM; inhibition of melanoma cell migration by approximately 45%." (PMID 39594665, 2024). "ITG αVβ3 acts as a receptor for Vitronectin, promoting cell adhesion and spreading, which contributes to melanoma metastasis." (PMID 38243233, 2024). "Interactions between CD47 and αvβ3 enhanced binding of ovarian and breast cancer cells and spreading of melanoma cells on vitronectin-coated substrates, as well as chemotaxis of prostate cancer and melanoma cells towards collagen." (PMID 37958404, 2023). "Previous research also confirmed that M21 human melanoma cells not only lost the ability to attach to vitronectin but showed a dramatic reduction in tumorigenicity when lacking integrin αv gene expression." (PMID 33834020, 2021). "The pre-incubation of melanoma cells with TAP7f inhibited cell adhesion to both fibronectin and vitronectin in a concentration-dependent manner." (PMID 32158394, 2020). "The overexpression of NOV enhanced the adhesion of melanoma cells to laminin and vitronectin through an up regulation of integrin α7β1 and αVβ5." (PMID 28412738, 2017). "Two melanoma cell lines C8161.9 and M14 both express high levels of αvβ3 integrin and adhere to vitronectin." (PMID 19400942, 2009). "In vivo, such an interaction between melanoma cells and Vitronectin could perhaps play a role in the release of extracellular lipidosomes, and thus stimulate lymphatic metastasis." (PMID 38243233, 2024). "The binding of all three melanoma cell lines to vitronectin was comparable to VCAM-1." (PMID 37894438, 2023). "The high expression of VTN was related to poor prognosis in melanoma patients." (PMID 36676646, 2022). "The interaction of melanoma cells with extracellular matrix proteins is one of the initial steps crucial for metastatic dissemination and we found that TAP7f inhibited cell adhesion to the immobilized matrix proteins vitronectin and fibronectin." (PMID 32158394, 2020). "Five proteins were selected for validation as prognostic factors in 348 melanoma patients and 100 controls by ELISA: serum amyloid A and clusterin; immune system proteins; the cell adhesion molecules plakoglobin and vitronectin and the antimicrobial protein dermcidin." (PMID 27216146, 2016). "In melanoma, integrin αVβ3 supports adhesion to ECM components such as fibronectin and vitronectin, thereby facilitating cell migration and invasion." (PMID 41465475, 2025). "To further validate the biological effect of LGRFYAASG-pen, we performed adhesion assays with KS1767 human Kaposi’s sarcoma, KRIB human osteosarcoma, B16F10 murine melanoma and Lewis lung mouse carcinoma (LLC) cell lines on fibronectin- or vitronectin-coated wells." (PMID 28652618, 2017). "SK-MEL-28 and HT144 melanoma cells were treated with 0.8 μM simvastatin for 24 hours to study the effect of simvastatin on adhesion to the ECM proteins, fibronectin, laminin, collagen type I, vitronectin and collagen type IV." (PMID 18199328, 2008).
prostate carcinoma (17 papers, 2007 to 2024). A carcinoma that arises from epithelial cells of the prostate gland. "Using MS-GUIDE we identified fibronectin and vitronectin as candidate biomarkers for prostate cancer risk stratification." (PMID 35477343, 2022). "VTN was previously identified as a serum-derived component that drives the differentiation of prostate cancer stem cells, which is in turn related to tumorigenesis." (PMID 35477343, 2022). "Intriguingly, VTN can also be detected to be secreted to blood serum in prostate cancer patients and act as circulating biomarker when combined with PSA (prostate-specific antigen) for early diagnosis of prostate cancer." (PMID 30819137, 2019). "αvβ3 integrin is reported to be crucial for breast and prostate cancer skeletal metastasis and binds to osteopontin, fibronectin and vitronectin." (PMID 24587138, 2014). "Expression of integrin αv is also required for the acquisition of a metastatic stem/progenitor cell phenotype in human prostate cancer, and vitronectin/αvβ3 interaction also induces breast and prostate cancer stem cell differentiation and tumor formation." (PMID 22567280, 2012). "Transformation of LNCaP to an androgen-independent model of prostate cancer, LNCaP-19 resulted in increased cell proliferation, migration, in vivo invasive ability, and adhesion to vitronectin and fibronectin." (PMID 24213501, 2012). "Tumour cell α5β1 and αvβ3 mediate adhesion of prostate cancer cells to endothelial cells through binding cell surface fibronectin and vitronectin." (PMID 24213501, 2012). "Doxycycline induction of uPAR in both prostate cancer cell lines however, lead to a pronounced increase in the level of attachment indicating that induced uPAR is biologically functional in mediating vitronectin matrix adhesion." (PMID 17509140, 2007). "Moreover, there was a reduction in attachment of TNBC and prostate cancer cells to vitronectin and fibronectin in ERK5 knockout cells via reduction in the FAK/proline-rich tyrosine kinase 2 (PYK2) interaction." (PMID 33572742, 2021). "β1-integrin signaling via the vitronectin (VN) receptors increased FAK and ERK5 activation and promoted TNBC and prostate cancer cell adhesion to the ECM and micromotion in vitro Adhesion of cancer cells to ECM was inhibited in the presence of VN blocking antibodies." (PMID 33572742, 2021).
diabetes (12 papers, 2011 to 2026). "Alterations in vitronectin glycosylation have been associated with an impaired function of endothelial cells observed in patients with hyperglycemia, vascular disease, and diabetes." (PMID 39593747, 2024). "Hence elevated AGEs in diabetes are likely to disrupt vitronectin/integrin interaction and subsequent osteoclast maturation, which may shift the bone remodeling balance and predispose to bone fragility in diabetes." (PMID 35388291, 2022). "And the AUC was increased from 0.625 to 0.806 when vitronectin was used together with maternal age and history of diabetes." (PMID 32724825, 2020). "Vitronectin has been found to be upregulated in the serum of patients with early-stage DR and involved in diabetes-induced angiogenesis that occurs in late-stage DR." (PMID 32933222, 2020). "This resulted in the same model comprising only maternal age, family history of diabetes and vitronectin (AUC = 0.806)." (PMID 30917176, 2019). "Although few previous studies have investigated the glycation of Tie-2, a large number of proteins have been verified to be glycated in diabetes mellitus in vivo, including vitronectin, fibronectin, PDGFR-β, and so on, which is at least partly in agreement with the findings in the present study." (PMID 35806141, 2022). "Using proteomic research methods, 2D electrophoresis and mass spectrometric analysis, increased concentrations of the complement system sub-components C1r, C3 and C4-B, α-1-antitrypsin and vitronectin were detected in patients with type 2 diabetes mellitus compared to the control group." (PMID 34948066, 2021). "In addition, vitronectin remained a significant contributor when combined with family history of diabetes alone or together with maternal age." (PMID 30917176, 2019). "The plasma vitronectin levels are increased in diabetes with nephropathy." (PMID 21414238, 2011). "FN1 and VTN, like other factors involved in the coagulation process, are known to increase not only in stroke patients but also in CVD and diabetes patients." (PMID 32466277, 2020).
neuroblastoma (11 papers, 2008 to 2025). Neuroblastoma (NB) is the most common solid, extracranial childhood tumor. "The high amount of vitronectin found in neuroblastoma biopsies has been associated with poor prognosis." (PMID 39201421, 2024). "In neuroblastoma (NB), vitronectin (VN), an extracellular matrix protein, has been linked to poor prognosis and appears as a promising therapeutic target." (PMID 36425532, 2022). "Vitronectin, as an extracellular matrix anchorage glycoprotein related to a stiff matrix, is present in a particularly increased quantity and specific distribution in high-risk neuroblastoma." (PMID 33109237, 2020). "Other studies have used scaffolds composed of silk to create hypoxic gradients, to study the response to integrin inhibition after incorporation of vitronectin, and to model the interactions between neuroblastoma cells, macrophages, and NK cells." (PMID 40874091, 2025). "Together, these data indicated that LIN28B counteracts the differentiation stimuli provided by FN, LM, and VTN to neuroblastoma cells." (PMID 40679030, 2025). "The range of vitronectin in neuroblastoma patients range from 52.4 to 870 μg mL−1, with a suggested cut-off of 361 μg mL−1 as this is when patients over the age of 18 months had worse prognosis." (PMID 40653949, 2025). "Vitronectin release was higher by neuroblastoma cells cultured in 3D models than in the monolayer and was still elevated when cells were grown in 3D scaffolds with cross-linked vitronectin." (PMID 39201421, 2024). "Three of the neuroblastoma cell lines secreted vitronectin to culture media when cultured in a monolayer and 3D models." (PMID 39201421, 2024). "Vitronectin concentration was quantified using ELISA in culture media of four neuroblastoma cell lines grown in a monolayer and in 3D models, and in the plasma of 114 neuroblastoma patients." (PMID 39201421, 2024). "We used immunohistochemistry and image analysis tools to characterize vitronectin expression and to test its prognostic value in 91 neuroblastoma patients." (PMID 31117974, 2019). "To better understand the effect of vitronectin, we studied its in vitro expression using commercial neuroblastoma cell lines and in vivo using intra-adrenal gland xenograft models by immunohistochemistry." (PMID 31117974, 2019). "Vitronectin oligomers are toxic to cultured neuroblastoma and retinal pigment epithelium (RPE) cells, possibly via a membrane-dependent mechanism, as they cause leakage of synthetic vesicles." (PMID 18939994, 2008). "Vitronectin could be considered a new plasma prognostic biomarker in neuroblastoma and warrants confirmation in collaborative studies." (PMID 39201421, 2024). "Our aim was to assess vitronectin as a potential circulating biomarker of neuroblastoma prognosis." (PMID 39201421, 2024). "Drugs inhibiting vitronectin interactions with cells and/or the extracellular matrix could represent a significant improvement in survival for neuroblastoma patients." (PMID 39201421, 2024). "In this study, we examined vitronectin expression in neuroblastoma to investigate whether this molecule takes part in cell-cell or cell-extracellular matrix interactions that may confer mechanical properties to promote tumor aggressiveness." (PMID 31117974, 2019). "PAN has been shown to enhance the survival of neuroblastoma cells and PEG, when enriched with vitronectin, improved neuroblastoma cell adhesion." (PMID 40874091, 2025). "Vitronectin, laminin, fibronectin were mainly absent in undifferentiated NB tumors, and the neuroblast cell population of ganglioneuroblastoma (GNB) tumors, but the proteins were present in gangliocytic cells and their adjacent extracellular matrix, as well as in SCs." (PMID 36231134, 2022).